MTOR (mechanistic target of rapamycin kinase)
Diseases named in the same sentence as MTOR in open-access papers (continued):
Sharing a sentence is not in itself a finding about the gene and the disease.
glioblastoma (continued). "Interplay between mTOR and PRMT5 has already been identified in different cell types, including T-lymphocytes B-cell lymphoma and glioblastoma." (PMID 35757005, 2022). "Yin reported that curcumin increases the effectiveness of temozolomide against U87 glioblastoma cells by increasing ROS levels, inhibiting AKT/mTOR signaling, and promoting apoptosis." (PMID 35977996, 2022). "In patients with glioblastoma, high protein expression of YB-1 correlated with increased expression of CCT4 and mLST8 and activated mTOR signaling." (PMID 35239512, 2022). "Here, we systematically examined the effects of ipatasertib on patient-derived glioblastoma cells and additionally compared the results with four other SMIs addressing targets in the PI3K/AKT/mTOR and MAPK signaling pathway with different mechanisms of action." (PMID 36013437, 2022). "Therefore, it could be speculated that increasing autophagy above a certain threshold through excessive ROS generation and subsequent modulation of AMPK/mTOR/ULK1 pathway is responsible for the synergistic cytotoxicity of AA+MD combination in U251 glioblastoma cells." (PMID 35368869, 2022). "Wormannin treatment significantly reduced glioblastoma-derived EVs-induced PI3K-Akt upregulation, as demonstrated by reduced expressions of p-PI3K, p-Akt, and p-mTOR after Wortmannin treatment." (PMID 35022057, 2022). "In glioblastoma, lncRNA SNHG20 positively regulated the PI3K/AKT/mTOR pathway by elevating the levels of p-PI3K, p-AKT, and p-mTOR." (PMID 36359888, 2022). "Recently, it has been reported that the PI3K/Akt/mTOR/HIF-1α pathway is involved in enhancing the migration and invasion of human glioblastoma cells under hypoxia." (PMID 35360199, 2022). "Additionally, research data have indicated that voxtalisib-targeted inhibition of PI3K/mTOR is a promising treatment strategy to reduce the tumour burden of patients with glioblastoma (GBM)." (PMID 35614940, 2022). "We found a consistent decrease in phosphorylation of mTOR and CREB after SB747651A exposure, and since the pro-tumorigenic role of mTOR in glioblastomas has been well established, mTOR inhibition is likely a partial functional mechanism of SB747651A." (PMID 33727611, 2021). "Glioblastoma stem cells (GSCs) play an undeniable role in tumor development by activating multiple signaling pathways such as Wnt/β-catenin and PI3K/AKT/mTOR that facilitate brain tumor formation." (PMID 33869033, 2021). "Other studies have shown that inhibition of PI3K/Akt/mTOR pathway and HIF-1α can inhibit the migration and invasion of human glioblastoma U87 cells." (PMID 34917504, 2021). "AnvirzelTM modulates the Akt/mTOR pathway, activates ERK and mTOR phosphorylation, decreases Akt and JNK1/2 phosphorylation in human glioblastoma cells U-87 MG after 48 h." (PMID 34943848, 2021). "Other agents that are under investigation in glioblastoma effecting this pathway are PI3K inhibitors (e.g., buparlisib, GDC-0084), dual PI3K/mTOR inhibitors (e.g., dactolisib) or mTOR inhibitors (e.g., AZD8055)." (PMID 34576168, 2021). "James S. Waldron etc. found that PTEN loss associated with activation of the PI3K-Akt-mTOR pathway and led to a autologous T-cell apoptosis in glioblastoma, which can be diminished by treatment with inhibitors of PI3K-Akt-mTOR pathway." (PMID 33874915, 2021). "In particular, in glioblastoma multiforme cells, OLE promoted the expression of different miRNA including miR-13745 that is involved in the downregulation of Akt/mTOR signaling pathway." (PMID 33633156, 2021). "In glioblastoma multiforme (GBM), mTOR is activated and autophagy is inhibited." (PMID 34065350, 2021). "Regarding signal transduction, many of the interacting proteins mapped to frequently deregulated signaling pathways in glioblastoma such as the EGFR-MAPK, PI3K-AKT- mTOR and Small GTPase signaling hubs; a finding in line with our phosphoproteome analysis." (PMID 34771501, 2021).
glioblastoma (continued). "Luteolin downregulated the protein expression levels of phosphorylated Akt, mTOR, p70S6K, and MAPK, also induced caspase and PARP cleavages in glioblastoma cells and promoting cell cycle arrest." (PMID 34049576, 2021). "Current drugs specifically targeting EGFR tyrosine kinase activity or selectively inhibiting mTOR, a PI3K/Akt downstream signal transducer showed little efficacy in treatment of primary glioblastoma." (PMID 34440090, 2021). "The PI3K/AKT/mTOR pathway is activated in 90% of all Glioblastoma multiforme (GBM) tumors." (PMID 34831287, 2021). "Already 4 h of culture with 50 μM canavanine in arginine-free medium evoked pronounced changes in the phosphorylation status of proteins involved in protein synthesis such as 4EBP1 (mTOR pathway) and eIF2α (GCN2 pathway) in both glioblastoma cell lines." (PMID 33008000, 2020). "In contrast, in glioblastoma cells U251 and U87, berberine induces autophagy by inhibiting the AMPK/mTOR/ULK1 pathway." (PMID 33233671, 2020). "In fact, mTOR-dependent ATG inhibition strongly correlates with the presence of EVs, which in turn promotes glioblastoma cancer stem cells (GSCs) self-renewal, proliferation, and infiltration." (PMID 32887296, 2020). "In glioblastoma, miR-451 is expressed in the presence of high levels of glucose and upregulates the LKB1/AMPK/mTOR pathway, which finally leads to proliferation." (PMID 32707662, 2020). "Some researchers have found that cytotoxic drug withaferin A, which is involved in oxidative stress, can increase the sensitivity of glioblastoma to TMZ treatment by reducing MGMT expression and activating apoptosis induced by Akt/mTOR signaling pathway." (PMID 32086739, 2020). "Few studies also confirmed that Akt and mTOR play a vital role in order to exhibit the reliability of CSCs in several cancers such as; GCTB, neuroblastoma and glioblastoma." (PMID 32351329, 2020). "As various synergies have been tested and since the conventional treatment of glioblastoma involves beam radiation, the impact of LNC-rapa on mTOR phosphorylation in U87MG cells was also tested after exposure to 8Gy irradiation." (PMID 33718332, 2020). "RAS effector signaling pathways such as PI3K/mTOR and ERK are frequently dysregulated in glioblastoma." (PMID 33235998, 2020). "Leptin has been shown to upregulate various intracellular signaling pathways linked to excessive proliferation, growth, migration, and invasion in various glioblastoma cell lines including NF-κB, p38-MAP Kinase, JAK/STAT3 and PI3K/Akt/mTOR/P70S6K." (PMID 33316976, 2020). "Glioblastomas (GBs) frequently display activation of the epidermal growth factor receptor (EGFR) and mammalian target of rapamycin (mTOR)." (PMID 31510109, 2019). "XL765, a dual mTOR and PI3K oral inhibitor, is the first member of this class to be examined in glioblastoma patients; a phase I trial combining radiation therapy (RT)/TMZ with XL765 in patients with recurrent gliomas is under way." (PMID 31013819, 2019). "Western blot analysis revealed that stellettin B treatment dose-dependently downregulated Akt, mTOR, and ribosomal protein S6 phosphorylation in both the U87MG and GBM8401 glioblastoma cells within 24 h." (PMID 30769863, 2019). "ENMD-2076 induced glioblastoma cell cycle arrest in G2-M phase and apoptosis by inhibiting PI3K/AKT/mTOR signaling pathways." (PMID 31706255, 2019). "In glioblastoma cells, SEMA3F inhibits the phosphorylation of Akt (T308 and S473), Erk, mTOR, and S6K, the mTOR downstream molecule, via NRP2 and plexin A1 receptors." (PMID 30532711, 2018). "Additionally, being the U87MG cell line endowed with glioblastoma stem cells (GSCs), we also investigated the role of the PTEN/PI3K/AKT/mTOR pathway in this specific cell population, which is responsible for GBM relapse." (PMID 29692710, 2018). "Here, we showed that silibinin inhibited the phosphorylation of mTOR, p70S6K, and 4E-BP1 in human glioblastoma cells." (PMID 29780826, 2018).
glioblastoma (continued). "In glioblastoma CSCs, cross-inhibitory regulation between the MEK/ERK and PI3K/mTOR signalling cascades contributed to self-renewal and tumorigenic capacity." (PMID 29385093, 2018). "A recent study showed that treatment with the mechanistic target of rapamycin kinase (mTOR) inhibitor, rapamycin, induced rapid CCND1 mRNA decay due to the increased TTP expression in glioblastoma cells." (PMID 30380668, 2018). "Therefore, Triciribine and Rapamycin, as inhibitors of the AKT/mTOR pathway, may be further studied for their potential use as adjunct therapy in the treatment of neuroblastoma and glioblastoma, given their in vitro ability to successfully inhibit and eradicate an enriched population of CSC." (PMID 30323898, 2018). "It has been shown in the context of glioblastoma that cross-inhibitory regulation between the MAPK and PI3K/mTOR pathways by p70S6K contributes to both tumorigenic and self-renewal capacity of cancer stem-like cells." (PMID 28512266, 2017). "In fact, the most robust results for glioblastoma were obtained when a combination of MAPK and PI3K/mTOR inhibitors was used in comparison to individual inhibitors." (PMID 28512266, 2017). "We observed that inhibition of the PI3K/mTOR pathway induced cell cycle arrest in G1 phase, in both U87MG adult and SF188 pediatric glioblastoma cell lines." (PMID 28624789, 2017). "A brain-penetrant PI3K/mTOR inhibitor, GNE-317, was shown to have anti-tumor activity in orthotopic models of glioblastoma." (PMID 28493046, 2017). "Recent studies using adult glioblastoma models demonstrated that combinatorial treatment with TMZ and the PI3K/mTOR inhibitors voxtalisib or NVP-BEZ235 significantly reduced tumour growth rates and prolonged median survival of tumour-bearing mice." (PMID 28704425, 2017). "As witnessed by multiple experimental and neuropathological findings, mTOR upregulation plays a major role in the development of the aggressive phenotype of glioblastoma (GBM, WHO grade IV astrocytoma), thus influencing prognosis and determining response to therapies." (PMID 29259984, 2017). "Withaferin A, an oxidative cytotoxic agent, resensitizes temozolomide-resistant glioblastomas via MGMT depletion and induces apoptosis through AKT/mTOR pathway inhibitory modulation." (PMID 29181405, 2017). "PI3K signaling increases glioblastomas formation and tumor progression in mouse-engineered models, launching PI3K and its effecter mTOR as convincing targets." (PMID 27329594, 2016). "Other dual-therapy regimens being examined are combined inhibition of AKT/mTOR and MDM2 in glioblastoma, and combined c-MET and EGFR in non-small lung cancer." (PMID 26955870, 2016). "This is of particular interest to Glioblastoma, as in 88% of all glioma genetic alterations have been found in the PI3-Kinase/Akt/mTOR network, a signaling cascade for which a multitude of pharmacological inhibitors are currently on the market." (PMID 26121251, 2015). "BEZ235 has been shown to be effective in xenograft models for glioblastoma at higher doses; however, we were unable to dose at a level required to achieve either inhibition of PI3K and mTOR targets or a survival effect." (PMID 25431423, 2015). "Preclinical studies have shown that the dual PI3K/mTOR inhibitor BEZ235 demonstrated antitumor activity in pancreatic cancer and glioblastoma, amongst others." (PMID 26560145, 2015). "However, due to its complex role in several cellular processes, in particular autophagy, which may lead to increased or reduced cell survival and the upregulation of ERK signaling upon its inhibition, mTOR is generally considered a difficult target in glioblastoma." (PMID 26056598, 2014). "As mutations in the mTOR signalling pathway in GBM frequently result in hyperactive PI3-K/mTOR signalling, promoting cell survival and protein synthesis, we investigated whether mTOR kinase activity has a role in regulating levels of MGMT protein expression in human glioblastoma cells." (PMID 24909675, 2014).
glioblastoma (continued). "Previous studies showed that suppression of CK2 induces autophagic cell death through modulation of the mTOR and MAPK signaling in human glioblastoma cells." (PMID 25486409, 2014). "Indeed, studies show that a 10-day treatment of U87 primary glioblastoma multiforme, (GBM) xenografts with Torin 1 resulted in a robust activation of the PI3K/Akt/mTOR pathway and tumor growth suppression by over 99%." (PMID 24244833, 2013). "The phosphorylation status of ERK1/2 was not affected by rapamycin, although crosstalk between the PI3k/Akt/mTOR pathway and the MEK/ERK pathway has been reported in glioblastoma stem-like cells." (PMID 24231729, 2013). "The current drugs that specifically target the tyrosine kinase activity of EGFR or selectively inhibit the mammalian target of rapamycin (mTOR), a PI3K/AKT downstream signal transducer showed little efficacy in treatment of primary glioblastoma." (PMID 22494416, 2012). "We chose the PTEN null glioblastoma U-87 MG cell line as a first model to explore the combination of RAD001 and BEZ235, and monitored mTOR pathway inhibition by western blot analysis." (PMID 23155392, 2012). "The same group denoted that this relationship also applies to p-mTOR and its target proteins p-4E-BP1 and p-p70S6K, which was illustrated in their similar distribution in perinecrotic areas of glioblastomas." (PMID 22530122, 2012). "Therefore, the crucial role of the PI3K/AKT/mTOR pathway in GSC survival, proliferation, and resistance makes it a highly attractive therapeutic target for combating glioblastoma aggressiveness and recurrence." (PMID 40867215, 2025). "In human glioblastoma cells, α-KG has been shown to enhance PDPK1 transcription by reducing the inhibitory histone modification H3K27me3, thereby promoting the activation of the PI3K/Akt/mTOR pathway." (PMID 41428315, 2025). "One of the key drivers of glioblastoma progression is the dysregulation of several critical signaling pathways, including those involving the EGFR and the phosphatidylinositol-3-kinase (PI3K)/mammalian target of rapamycin (mTOR) axis." (PMID 40650170, 2025). "It has also been shown to modulate key intracellular signaling pathways, such as phosphoinositide 3-kinase (PI3K)/protein kinase B (AKT)/mammalian target of rapamycin (mTOR) and mitogen-activated protein kinase (MAPK), in cell lines including glioblastoma U373, H7, and HAP1." (PMID 40004027, 2025). "Several studies have shown that ET1 increases the activation and expression of MMP2, -9 and -13 in colon cancer, chondrosarcoma, osteosarcoma, and glioblastoma cells via focal adhesion kinase (FAK), phosphatidylinositol 3-kinase (PI3K), AKT, mammalian target of rapamycin (mTOR), and NF-κB." (PMID 38785410, 2024). "Glioblastoma patients with an activated PI3K/Akt/mTOR pathway also have a worse prognosis than patients without oncogenic activation of the pathway." (PMID 39767683, 2024). "Also, mutations and rearrangements affecting PTEN, PI3K family, and MTOR genes, the key participants in the PI3K/AKT/mTOR signaling axis, were more frequent in IDH—wildtype glioblastoma (80%) compared with LGG (38%)." (PMID 39684714, 2024). "Studies have shown metformin’s efficacy in reducing cellular proliferation, inducing cell cycle arrest, and enhancing apoptosis, especially in glioblastoma through mechanisms that include the modulation of the mTOR/S6K1 pathway and direct action on glioblastoma stem cells (GSCs)." (PMID 38891882, 2024). "The researchers found that polypeptide N-Acetylgalactosaminyltransferase 12 (GALNT12) expression was highly linked with poor prognosis in glioblastoma, demonstrating that GALNT12 in U-87 MG glioblastoma cells mediates cell proliferation, migration, and invasion through the PI3K/Akt/mTOR pathway." (PMID 39728102, 2024). "Although the role of RPS4X in glioblastoma has not been reported yet, it should act through the mTOR signaling pathway." (PMID 39513861, 2024).
glioblastoma (continued). "In glioblastoma, PRMT5 activity conferred therapeutic resistance to mammalian target of rapamycin (mTOR) inhibitors by mediating the methylation of heterogeneous nuclear ribonucleoprotein 1 (hnRNP A1) to promote the translation of cyclin D1 and c-MYC, leading to drug resistance." (PMID 39703687, 2024). "Furthermore, YAP/TAZ have been shown to crosstalk with other signaling pathways, such as AKT, mTOR, and WNT, which are dysregulated in glioblastoma." (PMID 37366874, 2023). "A combination of sorafenib and another mTOR inhibitor, everolimus, appears to have fewer toxic side effects in recurrent glioblastoma patients, however, this treatment regime still fails to improve patient survival (NCT01434602)." (PMID 37857607, 2023). "We confirmed that silencing mTOR signaling components (rictor or raptor) selectively reduced HeLa cell viability in OXPHOS conditions, and these results were also consistent in glioblastoma cells." (PMID 36831501, 2023). "Furthermore, it induces cell death in glioblastoma resistant to mechanistic targeting of rapamycin (mTOR) inhibition when J007 and the PP242 (mTOR inhibitor) are simultaneously applied." (PMID 38139353, 2023). "In glioblastomas, the PKI3/Akt/mTOR pathway may have distinct and specific functions according to the survival needs of tumor cells." (PMID 37273792, 2023). "Since AKT mutations have not been observed in glioblastoma, the emphasis has been placed on PI3K and mTOR inhibitors." (PMID 37857607, 2023). "Depletion of FilGAP did not affect mTOR activity in U-87MG, a highly malignant glioblastoma, but significantly decreased AKT phosphorylation in the presence of a PI3K inhibitor." (PMID 38065968, 2023). "4, 5-Dimethoxycanthin-6-one could reduce cell proliferation and cell cycle arrest, and increased cell apoptosis by targeting the LSD1 mediated AKT/mTOR and MAPK signaling pathways in glioblastoma." (PMID 35042538, 2022). "First, glioblastoma cells were exposed to different doses of multi-kinase inhibitor dactolisib (PI3K, mTOR), pan-AKT inhibitors ipatasertib and MK-2206, multi-kinase inhibitor regorafenib (e.g., various receptor tyrosine kinases, B-RAF), or MEK inhibitor trametinib, respectively." (PMID 36013437, 2022). "We have previously demonstrated that Si306 and pro-Si306 inhibit Src tyrosine kinase activity in U87 and U87-TxR glioblastoma cells, along with the activity of upstream and downstream members of the Src signaling pathway, including components of the PI3K/Akt/mTOR axis." (PMID 36294938, 2022). "By focusing on the AMPK/mTOR/ULK1-pathway, berberine stimulates autophagy in glioblastoma." (PMID 36144625, 2022). "Some WA properties which are collected from studies on glioblastoma are antiproliferative activities and modulating MAPK, JAK/STAT, and Akt/mTOR signaling, induction of apoptosis and cell cycle arrest, modulation of HSP60/HSP70 chaperones, and effect on DNA damage and repair mechanisms." (PMID 36193062, 2022). "In human SHG44 glioblastoma cells, the RES/temozolomide combination has revealed additional antiproliferative effects upon inhibition of mTOR signaling and downregulation of the antiapoptotic Bcl-2 protein and increase in ROS production, and subsequent activation of AMPK." (PMID 35328780, 2022). "Further, the reduced viability of U251 cells treated with MET was found to be related with the reduction of hypoxia-inducible factor (HIF-1α) and vascular endothelial growth factor (VEGF), key actors of glioblastoma angiogenesis, as well as with the inhibition of PI3K/mTOR axis." (PMID 35326565, 2022). "RapaLink-1 has been shown to be efficacious in orthotopic mouse models of glioblastoma, but inhibition of mTOR in the periphery does not contribute to efficacy." (PMID 36104566, 2022). "Carnosine inhibits glioblastoma growth, but independent of PI3K/Akt/mTOR signaling with a significant reduction of Akt phosphorylation in the U87 glioblastoma cell line." (PMID 34203479, 2021).